GSDMD (gasdermin D)
Diseases named in the same sentence as GSDMD in open-access papers (continued):
Sharing a sentence is not in itself a finding about the gene and the disease.
tumor (continued). "In the future, it is necessary to construct a GSDMD-deficient mouse model to probe the effects of pyroptosis as a drug target on gliogenesis and the tumor immune microenvironment." (PMID 38304430, 2024). "In vivo studies using wild-type and GSDMD-deficient mice further substantiated DMB’s anti-tumor effects, which were dependent on GSDMD expression." (PMID 39587093, 2024). "They concluded that alcohol intake is associated with methylation patterns at two CpG sites (cg03199996 and cg07382687) located in genomic regions associated with tumor suppressor activity (GSDMD and HOXA5 genes)." (PMID 39125744, 2024). "We further detected the expression of ferroptosis‐associated proteins (HMGCR, GPX4) and pyroptosis‐associated proteins (such as NLRP3, GSDMD) in tumor tissues by using immunohistochemistry or western blot." (PMID 38178583, 2024). "Here the authors report a toolbox of gasdermin D variants for induction of pyroptosis, showing that, when combined with intratumoral expression of cytokines (IL-1β, IL-12, or IL-18), anti-tumor immune responses in preclinical models are enhanced." (PMID 39737979, 2024). "Intratumoral injection (i.t.)followed by electroporation of a plasmid encoding NT GSDMD resulted in tumor regression and prolonged survival compared to the control group where tumors were electroporated with empty vector." (PMID 39737979, 2024). "In this section, we aim to provide potential explanations for the observed heterogeneity in GSDMD-associated disease outcomes.Genetic alterations within tumor cells can significantly impact the expression and functionality of GSDMD." (PMID 38002346, 2023). "Membranous GSDMD expression is associated with CD68+ macrophages in the tumor center and CD8+ T cells in the tumor front, whereas nuclear GSDMD exhibits the opposite association." (PMID 38066523, 2023). "Tumor-associated macrophages are involved in pyroptosis through the classical pathway induced by the caspase-1 cleavage of GSDMD and the pathway mediated by the caspase-8 cleavage of GSDME and the granzyme action of GSDMB." (PMID 37542283, 2023). "Conversely, overexpression of GSDMD has been associated with larger tumor sizes, later TNM stages, and poorer survival rates in LUAD." (PMID 37077542, 2023). "Then, R software was used to analyze the immune cell infiltration, immune microenvironment score, and tumor mutational burden (TMB) analysis of GSDMD high- and low-expression groups in TCGA database." (PMID 37483501, 2023). "Conversely, GSDMD deficiency in APCs enhances the anti-tumor response and promotes the activation of CD8+ T cells." (PMID 38066523, 2023). "In endometrial cancer, GSDMD expression is significantly higher in cancer cells than in healthy endometrial tissue, and its expression is linked with anti-tumor immune properties and a more favorable prognosis." (PMID 35844522, 2022). "GSDMD is activated by caspase-1 to execute pyroptosis, and others suggested that GSDMD is associated with tumor growth." (PMID 36439171, 2022). "Our recent study clarified that STING-mediated Syk signaling attenuated the tumorigenesis of colitis-associated colorectal cancer (CAC) by enhancing GSDMD-driven pyroptosis of tumor cells." (PMID 36505474, 2022). "As an important molecular marker of pyroptosis, IL1β is generally released from the pore formed by oligomerized GSDMD and has been shown to be closely associated with the formation of an immunosuppressive microenvironment in several tumor types." (PMID 36199426, 2022). "Decreased GSDMD gene expression to 1.58-fold or less, and age to 53 years or less were linked to a higher risk of recurrence of a local tumor." (PMID 36120543, 2022). "In the current study, cox proportional hazards regression models revealed that GSDMD gene expression was 1.58-fold higher in cancer patients, and age 53 years was associated with a higher likelihood of local tumour recurrence." (PMID 36120543, 2022).
tumor (continued). "In contrast, sensitivity to the chemotherapy drug Gemcitabine was positively associated with the expression levels of GSDMD in tumor cells." (PMID 36138348, 2022). "Here, the tumor cells were genetically modified to achieve an inducible overexpression of the N-terminal domain of gasdermin D (GSDMD-NT) and effectively cause pyroptosis under a strict control." (PMID 36189310, 2022). "Previous studies have shown that the upregulation of GSDMD in tumor tissues was associated with a poor prognosis, due to its involvement in AKT-related signaling pathways." (PMID 36003332, 2022). "Collectively, these data indicate that Mll4 ablation impairs the enhancer activity and decreases the expression of DNA methyltransferases to predispose tumor cells to GSDMD-mediated pyroptosis." (PMID 36323669, 2022). "Natural products have been shown to activate NLRP3 by increasing ROS levels in tumour cells, which activates Caspase1, causing GSDMD to be cleaved and pyroptosis to occur." (PMID 36105214, 2022). "Higher GSDMD expression has been associated with aggressive traits, including a larger tumor size and more advanced TNM stage in lung cancer." (PMID 32778143, 2020). "In conclusion, CD147 is increased in patients with BC and showed association with GSDMD expression, leading to increased tumor proliferation." (PMID 32149134, 2020). "Methylations within DMR.A1 were positively associated with alcohol intake, and the related GSDMD gene has also been suggested to act as a tumor suppressor." (PMID 30940212, 2019). "However, a study by Berkel and Cacan found that higher levels of GSDMD are associated with decreased levels of NINJ1 in tumor tissues compered to adjacent stromal cells, which represents a different finding from previous studies." (PMID 41291696, 2025). "In the subcutaneous MC38 tumor model, anti–PD-1 treatment caused tumor regression, while progressive tumor expansion was observed in the Gsdmdfl/fl CD4cre mice after anti–PD-1 treatment, indicating the importance of GSDMD activation in CD4+ T cells for the therapeutic effectiveness." (PMID 40759573, 2025). "Tumor xenograft models further linked GSDMD to B cell, T cell and macrophage dynamics." (PMID 40491921, 2025). "Immunohistochemistry (IHC) and Western blot analyses of NLRP3‐overexpressing xenografts revealed elevated intratumoural levels of pyroptosis‐associated markers (Cleaved caspase‐1 and cleaved GSDMD) relative to control tumours after sustained drug administration." (PMID 38804602, 2024). "In addition, GSDMD in antigen-presenting cells suppressed the ability of macrophages and DCs to present tumor-associated antigens during PD-L1 inhibition and suppressed cytotoxic CD8+ T cell anti-tumor responses." (PMID 38773976, 2024). "Additionally, the antibody production and anti‐tumor response of GSDMD‐deficient mice were similar to those of wild‐type mice." (PMID 38900071, 2024). "In addition, upregulation of GSDMD was associated with higher tumor mutation burden and PD-1/PD-L1 expression." (PMID 37371484, 2023). "Moreover, GSDMD expression was significantly associated with tumor mutation burden, genetic alterations, and immune cell infiltration." (PMID 37371484, 2023). "Likewise, suppression of gastric cell proliferation is also observed with GSDMD but reduced expression was associated with mitigation of tumor proliferation and favorable prognosis in non-small cell lung cancer." (PMID 36605187, 2022). "Decreased expression of a primary mediator of pyroptosis, gasdermin D, is linked to enhanced cancer cell proliferation in vitro and tumor growth in vivo, whereas increased gasdermin E expression enhanced drug sensitivity of tumor cells." (PMID 33572196, 2021). "Evidence from DMR and FL analyses indicated that dietary folate and alcohol intake may be associated with genomic regions with tumor suppressor activity such as the GSDMD and HOXA5 genes." (PMID 30940212, 2019).
tumor (continued). "Additionally, targeting GSDMD in the TME could reduce tumor-associated inflammation and improve the effectiveness of cancer immunotherapies." (PMID 39759427, 2025). "Moreover, the inflammatory environment and related substances that are ubiquitous in the tumour environment, such as ATP released after cell death, can easily activate the NLRP3 inflammasome pathway and cleave gasdermin D (GSDMD) by activating caspase-1 and cause tumour-cell pyroptosis." (PMID 35289335, 2022). "This radical flux triggers spatially controlled pyroptosis via ROS/caspase‐1/GSDMD axis activation, as demonstrated through the therapy efficiency of tumor‐bearing mice." (PMID 40847518, 2026). "The synergistic photo‐thermoelectric catalysis triggers pyroptosis via reactive oxygen species‐caspase 1‐gasdermin D activation, eliciting robust systemic immunity that effectively eliminates the primary tumor and prevents tumor recurrence." (PMID 40847518, 2026). "In human BLCA, CD147 upregulates gasdermin D (GSDMD), a key effector of pyroptotic cell death, thereby promoting tumor cell proliferation and influencing inflammatory caspase activity." (PMID 41479915, 2025). "Next, we harvested tumor tissues and stained them with eEF2K, GSDMD, and GSDME immunofluorescence markers." (PMID 40567376, 2025). "LMNB2 overexpression attenuated the YY2 tumor suppressive effect, while blocking caspase‐1/GSDMD activation, IL‐1β levels, and cell death rate." (PMID 39903759, 2025). "Among these, CTSS was uniquely identified as the lysosomal protease capable of cleaving GSDMD, IL‐1β, and IL‐18 independently of caspase‐1, establishing a novel pathway of tumor‐specific pyroptosis induction." (PMID 40539828, 2025). "Immunofluorescence evaluations of Cyt C and GSDMD in the tumor tissues of orthotopic HS683‐Luc GB‐bearing nude mice confirmed that the expressions of these proteins were increased in GB cells after RES, α‐MEL or α‐MEL‐RES treatment." (PMID 40400263, 2025). "Consistently, Gsdmdfl/fl Vavcre mice, with specific depletion of GSDMD in hematopoietic cells, also displayed accelerated tumor growth when inoculated with MC38 or KPC tumors." (PMID 40759573, 2025). "We then explored the cellular distribution of GSDMD within the tumor microenvironment using the TISCH single-cell RNA sequencing database." (PMID 40491921, 2025). "In acute inflammatory microenvironments, low GSDMD expression in both tumor and immune cells facilitates tumor growth." (PMID 39994107, 2025). "T cell–specific depletion of GSDMD resulted in faster tumor growth in both MC38 and KPC subcutaneous tumor models and the KPC orthotopic tumor model, consistent with the earlier observations in conventional-knockout mice." (PMID 40759573, 2025). "Significantly, GSDMD deficiency or its inactivation in CD4+ T cells disabled CD8+ T cell–mediated antitumor immunity and caused tumor outgrowth in mice." (PMID 40759573, 2025). "Here, we show that activation of GSDMD in human tumor specimens mainly occurs in tumor-infiltrating leukocytes." (PMID 40759573, 2025). "The co‐treatment of HIC1 with the GSDMD inhibitor DMF led to an augmentation in both tumor volume and weight." (PMID 40279559, 2025). "In contrast, all the mice in the GSDMD‐ov group developed tumor metastasis in the lymph nodes (2/4 of the mice in the control group had tumor metastasis), with larger tumors, greater impacts on mouse weight, and higher GSDMD and Ki‐67 expression." (PMID 40178046, 2025). "The essential role of this pathway was further evaluated by knocking down GSDMD expression using shRNA, and the effects of H2 on tumor growth were assessed in an in vivo mouse model." (PMID 41140697, 2025). "NBS-1MT triggered pyroptosis by activating the caspase-1/GSDMD signaling pathway, leading to the suppression of primary and distant tumor growth." (PMID 40698137, 2025).
tumor (continued). "Concurrently, mitochondrial reactive oxygen species (ROS) accumulation upregulates zDHHC5 and zDHHC9 expression, promoting the palmitoylation of GSDMD and its N-terminal fragment, thereby amplifying the pyroptotic response in tumor cells." (PMID 39994107, 2025). "GSDMD expression shows differential correlations with immune, stromal, and tumor microenvironment (TME) scores across various cancers, revealing distinct patterns of immune cell infiltration and modulation of immune checkpoints and related genes." (PMID 40491921, 2025). "In conclusion, GSDMD exerts broad effects in both tumor and non-tumor diseases, primarily through its regulation of inflammatory responses." (PMID 39994107, 2025). "In non-tumor diseases, GSDMD mediates inflammatory responses by releasing pro-inflammatory cytokines, aggravating tissue damage." (PMID 39994107, 2025). "Collectively, our data suggest that GSDMD activation is crucial for immune cells to restrain tumor growth." (PMID 40759573, 2025). "Consistent with genetic data, GSDMD inhibition by DSF treatment in MC38 tumor–bearing mice also reduced the infiltration and function of T cells and NK cells, while changes in myeloid cells were minimal." (PMID 40759573, 2025). "This signifies that the knockdown of GSDMD reversed the tumor-suppressive and immune-enhancing effects of SNRPE targeting." (PMID 40386046, 2025). "To test this idea, we treated CD4+ T cells with tumor tissue supernatant during their in vitro activation, and found that cleavage of GSDMD and of caspase-8 were both weakened, leading to reduced production of IL-2." (PMID 40759573, 2025). "The expression of GSDMD in tumors is regulated in a more complex manner, where it can either promote immune evasion or, in some instances, induce tumor cell death." (PMID 39994107, 2025). "In CAR-T therapy, granzyme B cleaves GSDME in tumor cells, which triggers macrophage activation of caspase-1/GSDMD and leads to IL-1β/IL-6 release." (PMID 41291696, 2025). "Elevated GSDMD levels are associated with advanced TNM stages in NSCLC patients, and its knockdown inhibits tumor growth by activating the mitochondrial apoptotic pathway and suppressing the EGFR/AKT signaling pathway." (PMID 40141358, 2025). "To explore how GSDMD inactivation affected antitumor immunity, we performed flow cytometry analyses of tumor-infiltrating leukocytes (TILs) on day 18 after MC38 implantation." (PMID 40759573, 2025). "In non-tumor diseases, GSDMD promotes pathogen clearance and tissue repair by regulating the release of inflammatory cytokines." (PMID 39994107, 2025). "Epigenetic downregulation of NLRP3/GSDMD by histone deacetylase 2 (HDAC2) can reduce anti-tumor therapeutic efficacy." (PMID 41291696, 2025). "The question arises as to how the SNRPE targeting induces pyroptosis through the cleavage of caspase-1/GSDMD in tumor cells." (PMID 40386046, 2025). "The phenotypes of tumor growth advantage and lymphocyte function impairment in GSDMD-deficient mice were recapitulated in the KPC and B16-OVA tumor models." (PMID 40759573, 2025). "We further examined and verified a significant increase in GSDMD expression after neoadjuvant chemotherapy in the tumor tissues of OSCC patients and observed a significant association between high GSDMD expression and lymph node metastasis in OSCC patients." (PMID 40178046, 2025). "In non-tumor diseases, GSDMD expression and activity are markedly upregulated, driven by pathological conditions and tissue-specific microenvironments." (PMID 39994107, 2025). "Higher GSDMD levels were related to an adverse prognosis and cancer aggression (metastasis and larger tumor size)." (PMID 41291696, 2025). "Alterations in GSDMD expression in the tumor tissues of patients before and after neoadjuvant chemotherapy." (PMID 40178046, 2025). "Conversely, in chronic inflammatory microenvironments, GSDMD-mediated pyroptosis in immune cells triggers inflammatory responses that further promote tumor progression." (PMID 39994107, 2025).
tumor (continued). "The expression of GSDMD in tumor tissues is dynamically controlled by the interactions between tumor cells and immune cells." (PMID 39994107, 2025). "GSDMD was found to be aberrantly expressed in multiple tumor types and positively correlated with TMB, MSI, and immune checkpoint expression." (PMID 40491921, 2025). "In tumors, GSDMD demonstrates dual roles: it can suppress tumor growth or promote tumor proliferation and migration through immune suppression mechanisms." (PMID 39994107, 2025). "In cancer, pyroptosis exhibits dual roles: GSDMD overexpression in NSCLC correlates with tumor aggressiveness, while NLRP3 activation in HCC suppresses metastasis." (PMID 41235238, 2025). "Our findings highlight GSDMD as a potential biomarker for predicting immunotherapy response and as a modulator of tumor-immune interactions." (PMID 40491921, 2025). "We next assessed correlations between GSDMD expression and tumor immune infiltration in human cancers by analyzing the TISIDB and TIMER databases." (PMID 40759573, 2025). "The high expression of GSDMD protein initiated pyroptosis and activated the immune system, which produced a strong tumor immune response and inhibited tumor growth, providing a nanoplatform for cancer immunotherapy." (PMID 40698137, 2025). "Caspase-8 activation mediates GSDMD cleavage upon TCR activation, susceptible to suppression by tumor-derived factors." (PMID 40759573, 2025). "In non-tumor diseases, GSDMD expression is notably upregulated, while in tumor-related diseases, the changes in expression are more complex." (PMID 39994107, 2025). "A live attenuated version of the ZIKV vaccine has been shown to enter GBM tumor cells via αvβ5 and/or Ax1 receptors, which in turn induce apoptosis (caspase-3) and pyroptosis (GSDMD/IL-1β)." (PMID 41291696, 2025). "GSDMD-induced pyroptosis suppressed tumor growth in subcutaneous EC xenografts, revealing its tumor-suppressive role in EC." (PMID 40538398, 2025). "GSDMD can enhance tumor cell resistance to pyroptosis and augment the immune response of tumor cells." (PMID 39994107, 2025). "Through subcutaneous xenograft experiments, we demonstrated that GSDMD-mediated pyroptosis exerts tumor-suppressive effects through growth inhibition." (PMID 40491921, 2025). "For tumor diseases, the role of GSDMD-mediated pyroptosis is highly complex, as it can both promote tumor growth and suppress tumorigenesis." (PMID 39994107, 2025). "Subsequently, our findings discovered that HIC1 facilitated cell pyroptosis by transcriptionally activating the downstream target GSDMD, leading to an increase in tumor‐infiltrating CD8+ T cells." (PMID 40279559, 2025). "To determine the effector cells, whose functional impairment by GSDMD inactivation was responsible for the observed tumor growth acceleration, we used depleting antibodies to target specific immune populations." (PMID 40759573, 2025). "In contrast, in tumor diseases, GSDMD exhibits bidirectional regulatory functions, either suppressing tumor cell pyroptosis to promote tumor progression or modulating immune responses to inhibit tumor growth." (PMID 39994107, 2025). "In tumor diseases, GSDMD exhibits contradictory functions, potentially promoting or suppressing tumor progression depending on the context." (PMID 39994107, 2025). "Further mechanistic studies are necessary to elucidate how GSDMD interacts with immune checkpoint pathways, inflammasomes, and the tumor microenvironment." (PMID 40491921, 2025). "GSDMD protein levels are significantly upregulated in nonsmall cell lung cancer (NSCLC) when compared to matched adjacent tumor specimens." (PMID 40783818, 2025). "GSDMD in contrast is predominantly expressed by myeloid cells in the tumor, including macrophages and dendritic cells." (PMID 39224600, 2024). "To further confirm the mechanism, we demonstrated that pro‐IL37 was indeed secreted outside of tumour cells through GSDMD." (PMID 39500733, 2024).